SHBG (sex hormone binding globulin)
Diseases named in the same sentence as SHBG in open-access papers (continued):
Sharing a sentence is not in itself a finding about the gene and the disease.
Obesity (continued). "Many men given this diagnosis have a low level of sex hormone-binding globulin (SHBG) associated with obesity, type 2 diabetes (T2DM), dyslipidemia and non-alcoholic fatty liver disease (NAFLD)." (PMID 33014416, 2020). "Lower SHBG levels are associated with lower adiponectin levels in patients with obesity and metabolic syndrome, possibly by increasing hepatic lipogenesis thereby leading to downregulation of HNF-4α." (PMID 33139661, 2020). "In children, very few studies have investigated the association between SHBG and obesity and/or lipid profiles." (PMID 33291623, 2020). "A decline in testosterone is attributed partly to a decrease in sex hormone-binding globulin associated with obesity and an increased aromatase conversion of estradiol in adipocytes." (PMID 30567335, 2018). "An independent inverse association between SHBG and obesity as defined by body mass index (BMI) and waist circumference (WC) has been reported cross-sectionally and longitudinally." (PMID 29995902, 2018). "As a result of obesity, and its association with hyperinsulinemia, female testosterone can increase with a concomitant decrease in SHBG by having an effect on hepatic synthesis of SHBG." (PMID 29618342, 2018). "Obesity and high insulin levels are associated with lower levels of sex hormone binding globulin (SHBG)." (PMID 29713614, 2018). "As expected, SHBG was inversely associated with BMI, and it is well known that SHBG levels decrease in obesity, both in men and women." (PMID 30275830, 2018). "Lower SHBG levels have been widely associated with a higher risk of metabolic conditions, including diabetes, cholesterolemia, and obesity, and with adverse changes in fasting insulin, glucose, and BMI." (PMID 29075555, 2017). "The liner regression results showed that in the model adjusted for age, current smoking status, hypertension and overweight/obesity, the TyG was negatively associated with log-TT, log-E2, log-SHBG, log-FSH and log-LH (all P for < 0.01)." (PMID 29158535, 2017). "The conversion of testosterone to estradiol can increase in obesity conditions, but SHBG production is typically associated with obesity inversely." (PMID 27921025, 2016). "Many studies have linked lower circulating levels of SHBG to obesity, IR, MetS, T2DM, PCOS, and NAFLD." (PMID 26761949, 2016). "In men, obesity is associated with high estrogen levels, and low levels of testosterone and sex hormone binding globulin, thereby leading to greater estrogen bioavailability." (PMID 27377827, 2016). "This reduction in total testosterone levels is in part due to the obesity-associated lowering in sex hormone binding globulin (SHBG)." (PMID 27716209, 2016). "The findings suggest that obesity can be a cause of hypogonadism through the conversion of testosterone to estradiol in adipose tissue and decrease SHBG production." (PMID 27921025, 2016). "The same mechanism, augmented by decreased levels of sex hormone binding globulin (SHBG) leading to more available estrogen, is also proposed to explain why obesity increases risk of postmenopausal breast cancer." (PMID 26552431, 2015). "Both alcohol consumption and obesity measures (BMI and waist-hip ratio) were associated with circulating hormones, especially SHBG in a cross-sectional study." (PMID 26552431, 2015). "Obesity has been positively associated with estrogen in postmenopausal women and inversely associated with SHBG in both pre and postmenopausal women." (PMID 26352264, 2015). "Another factor associated with obesity is low levels of sex hormone binding globulin which results in increased bioavailable estradiol." (PMID 25309751, 2014). "(iii) Obesity is associated with lower levels of sex-hormone binding globulin (SHBG), which correlate with increased bioavailability of circulating oestrogens." (PMID 25338520, 2014).
Obesity (continued). "This rise in free circulating estrogen is further exacerbated by the reduced synthesis of the sex-hormone binding globulin (SHBG) due to the obesity-associated hyperinsulinemia." (PMID 23762064, 2013). "An alternative model is that the genes clustered with the UL gene and affecting the correlated phenotypes (serum SHBG level, age at menopause and obesity) would merely confound the association by virtue of their tight LD with the causal gene variants." (PMID 23555580, 2013). "Outside of the SHBG region we saw several SNPs with suggestive evidence of association, one of which (rs12596210) is intronic within the fat mass and obesity associated (FTO, Gene ID: 79068) gene." (PMID 22675492, 2012). "Apart from reduced estrogen levels, an increased concentration of androgens and low levels of SHBG have been suggested as the biological rationale for the association between obesity and reduced breast cancer risk among premenopausal women." (PMID 20181294, 2010). "Interestingly, obesity indicators mediated the associations of dietary inflammation and oxidative stress potential with infertility and SHBG." (PMID 40458178, 2025). "We hypothesize that theremight be a decrease in sex hormone-binding globulin concentration, caused by insulinresistance and obesity-related hyperestrogenism." (PMID 40215266, 2025). "Dietary inflammation and oxidative stress are strongly associated with the risk of infertility and serum SHBG levels, indicating that anti-inflammatory and anti-oxidative diets may mitigate fertility disorders that result from obesity." (PMID 40458178, 2025). "Furthermore, obesity is an independent risk factor for endocrine disruption: elevated blood serum total testosterone and insulin levels and reduced SHBG concentration levels." (PMID 40491594, 2025). "In most men with simple obesity, the mild to moderate reduction in serum testosterone is mediated through the lowering of circulating SHBG due to adiposity-associated metabolic abnormalities such as hyperinsulinemia, hypertriglyceridemia, and hepatic steatosis." (PMID 40052430, 2025). "Therefore, decreased SHBG is considered one of the major contributors to obesity-associated hypogonadism." (PMID 41301438, 2025). "SHBG rs1799941 was found to be a genetic risk factor for obesity-based hypogonadism in men." (PMID 40427034, 2025). "Obesity, which disrupts glucose-insulin metabolism, is associated with decreased SHBG levels." (PMID 40861046, 2025). "Obesity, as a body mass index of >30 kg/m2, is associated with low serum testosterone and sex hormone-binding globulin (SHBG) levels despite normal follicle-stimulating hormone (FSH) and luteinizing hormone (LH) levels, a condition known as functional hypogonadism." (PMID 39797269, 2024). "Furthermore, the causal effects decreased considerably after including obesity (BMI), alcohol intake frequency, SHBG, hyperandrogenemia, and fasting insulin in the multivariable MR analysis." (PMID 38318294, 2024). "In addition, high insulin levels as a result of obesity and/or T2D are associated with decreased SHBG synthesis, resulting in higher unbound and active sex hormones." (PMID 39467940, 2024). "In the sensitivity analysis excluding the participants who provided a blood sample for reproductive hormone assessment during the evening, some estimates attenuated slightly, leading to a loss of statistical significance for the association between maternal pre-pregnancy obesity and SHBG and LH." (PMID 37935951, 2024). "Additionally, obesity can alter sex hormone levels, causing elevated estrogen and androgen levels while reducing levels of sex hormone-binding globulin (SHBG)." (PMID 38021482, 2023). "The lower levels of testosterone and SHBG are linked with obesity and higher values of BMI." (PMID 37208686, 2023).
Obesity (continued). "Sex hormone-binding globulin prevents insulin resistance to endoplasmic reticulum stress in hepatocytes, reducing type 2 diabetes and counteracting the development of obesity caused by high-fat diets, and sex hormone-binding globulin improves insulin sensitivity by stimulating hepatocytes." (PMID 37600949, 2023). "Moreover, obesity is associated with insulin-induced reductions of sex hormone-binding globulin (SHBG), which increases the bioavailability of sex steroids including estradiol." (PMID 38027308, 2023). "The present studies show that SHBG concentrations and free testosterone concentrations increase after gastric sleeve surgery, emphasizing that not all observed changes in testosterone concentrations are caused by the effect of obesity and weight loss on SHBG concentrations." (PMID 37344792, 2023). "This curvilinear trend can be explained by the fact that obesity is associated with increased androgen precursor to estradiol peripheral conversion due to increased aromatase activities in bulky adipose tissue and reduced sex hormone binding globulin." (PMID 37305586, 2023). "Moreover, lower SHBG has been associated with older age, obesity, and lifestyle risk factors, such as being physically inactive and alcohol consumption, all closely related to liver fat accumulation." (PMID 37900132, 2023). "Previous studies found that circulating levels of SHBG could be upregulated by adiponectin, which was inversely associated with obesity." (PMID 36800955, 2023). "Therefore, the close interplay between SHBG levels and risk factors involved in the pathogenesis of NAFLD, obesity and MetS suggests SHBG as a potential therapeutic target in the management of these diseases." (PMID 36421197, 2022). "We hypothesize that exposure to certain phthalate metabolites is associated with low SHBG levels, high TT levels, obesity, and metabolic syndrome among women." (PMID 36149653, 2022). "In this cross-sectional study, exposure to certain phthalate metabolites could be associated with low SHBG levels, obesity, and metabolic syndrome depending on menopausal status." (PMID 36149653, 2022). "Observational epidemiological studies have reported associations between several hormonal, metabolic and inflammatory factors linked to obesity and endometrial cancer, including bioavailable testosterone, sex hormone-binding globulin (SHBG), oestradiol and fasting insulin." (PMID 35436960, 2022). "However, lower SHBG and higher estradiol were associated with obesity in postmenopausal women, while the levels of SHBG appeared inversely related to breast cancer risk in postmenopausal women." (PMID 35277131, 2022). "Low plasma SHBG levels are associated with obesity, IR, NAFLD and T2DM." (PMID 36267567, 2022). "Other obesity–cancer association mechanisms include obesity-induced chronic inflammation; increased aromatase expression, circulating levels of estrogen, insulin, leptin and ceruloplasmin; and decreased amounts of adiponectin and sex-hormone-binding globulin." (PMID 35741001, 2022). "Strikingly, the inverse association between obesity and SHBG was also more pronounced in women." (PMID 33715205, 2021). "Low plasma levels of SHBG are associated with several sex-steroid hormone-dependent diseases and have been reported to be an early indicator of cardiovascular risk in individuals suffering from obesity and metabolic syndrome." (PMID 34335746, 2021). "An inverse association between DNL and SHBG may explain the decreased SHBG levels that are observed in obesity, at least in women." (PMID 33715205, 2021). "The relationship of PCOS and obesity is highly complex and obesity is known to exacerbate risk of impaired glucose tolerance, dyslipidemia, metabolic syndrome and hyperandrogenemia by concomitantly suppressing hepatic SHBG synthesis." (PMID 33635862, 2021).
Obesity (continued). "The latest studies revealed that sex hormone-binding globulin (SHBG)—a serum protein released mainly by the liver—may participate in metabolic dysregulation, as its low serum level correlates with a risk for obesity, metabolic syndrome, and diabetes." (PMID 33808055, 2021). "Obesity and advancing age are associated with lower levels of total testosterone and SHBG." (PMID 34077443, 2021). "Indeed, HIV per se, obesity and increased SHBG are indicated as possible causes of functional hypogonadism." (PMID 33515211, 2021). "This lack of differences might be associated with the factors contributing to the SHBG level and/or obesity, such as pro-inflammatory markers and liver fat content." (PMID 33291623, 2020). "Obesity is an independent risk factor for several hormonal abnormalities, such as increased concentrations of testosterone and insulin, and reduced concentrations of the sex hormone-binding globulin, which inevitably influences the menstrual cycle." (PMID 30717736, 2019). "Serum concentrations of SHBG are also known to be negatively associated with obesity." (PMID 31810188, 2019). "It is well known that SHBG levels decrease with increasing obesity and rise with weight loss." (PMID 30321217, 2018). "In older men, obesity is strongly linked to SHBG and influences levels of circulating sex hormones." (PMID 29342161, 2018). "Relatively low levels of SHBG are also a risk factor for obesity, metabolic syndrome, and diabetes." (PMID 30046278, 2018). "This is the first study to show that the TyG reflecting insulin sensitivity is negatively associated with lower total T, E2, LH, FSH and SHBG concentrations after adjustment for potential confounders (age, current smoking status, hypertension and overweight/obesity)." (PMID 29158535, 2017). "For these reasons, it was hypothesized that stratifying subjects by their obesity status may influence the association between SHBG levels and arterial stiffness." (PMID 29213285, 2017). "However, the interaction between sex hormones and obesity during the menopausal transition is complex, since adipose tissue is active metabolically and associated with lower sex hormone-binding globulin (SHBG) levels." (PMID 27417630, 2016). "SHBG levels decrease with increasing obesity and rise with weight loss." (PMID 26761949, 2016). "Decreased testosterone concentrations in obesity and diabetes mellitus are linked to decreased sex hormone binding globulin (SHBG), whereas opioids may cause gonadal inhibition at the hypothalamic, pituitary and end-organ level." (PMID 26239687, 2015). "Obesity is associated with low levels of sex hormone-binding globulin (SHBG)." (PMID 23781314, 2013). "Obesity is inversely associated with both total testosterone and sex hormone-binding globulin." (PMID 23189072, 2012). "It has already been mentioned that obesity has been associated with decreased testosterone levels, a relation that was initially attempted to be attributed to either increased peripheral aromatization to estrogens or decreased SHBG concentrations." (PMID 19433001, 2009). "Obesity also decreases SHBG levels, which are inversely associated with prostate cancer risk." (PMID 18728645, 2008). "More specifically, obesity is associated with higher breast cancer risk among postmenopausal women through greater lifetime exposure to higher levels of estrogens produced in adipose tissue and lower SHBG production." (PMID 15694000, 2005). "In this current study, we performed a network two-sample MR study with the aim of determining whether SHBG levels are causally associated with stroke and its etiological subtypes via cardiometabolic traits, including obesity, blood pressure, glycemic and lipid phenotypes." (PMID 40728963, 2025). "Rather, obesity and excessive alcohol consumption both can cause damage to the liver in the form of fatty liver disease and steatohepatitis, and this fat accumulation and inflammation of the liver might in turn decrease synthesis of SHBG." (PMID 40766921, 2025).
Obesity (continued). "Notably, low levels of SHBG are associated with obesity and IR, two key components of MetS." (PMID 40863113, 2025). "Weight loss reduces insulin, sex hormone-binding globulin (SHBG), and estrogen levels; moreover, excess weight before conception is a major risk factor for fertility outcomes and it is well established that weight loss improves fertility in women with overweight and obesity." (PMID 37697017, 2024). "First, obesity and increased fat mass are known to cause decreased testosterone level, an anabolic hormone that stimulates bone formation, in men due to suppression of the hypothalamic‐pituitary‐testicular axis and insulin resistance−associated reductions in sex hormone binding globulin." (PMID 36926024, 2023). "Therefore, this study aims to explore whether E2, T, FSH, DHAS, and SHBG mediate the association between overweight/obesity and diabetes during the menopause transition period within the Study of Women’s Health Across the Nation (SWAN) cohort." (PMID 36767197, 2023). "Consistent with our hypothesis, our findings suggest that high levels of exposure to some phthalate metabolites are associated with lower SHBG levels, obesity, and metabolic syndrome to a greater extent among premenopausal women than among postmenopausal women." (PMID 36149653, 2022). "However, individual or composite exposure to HMW phthalates, especially from DEHP, DNP, DINCH, and BzBP, may have differential associations with SHBG levels, obesity, and metabolic abnormalities according to menopausal status." (PMID 36149653, 2022). "Meanwhile, low SHBG levels in subjects with obesity may be associated with increased liver fat." (PMID 33291623, 2020). "Indeed, in women with obesity, sex hormone-binding globulin (SHBG) levels are lower—associated with hyperinsulinemia and increased liver fat—a state related with higher diabetes risk in women—and further contributing to higher levels of free testosterone [8••]." (PMID 33033953, 2020). "However, whether the HNF4α alleles link low SHBG levels to obesity and metabolic disorders remains unclear." (PMID 30925463, 2019). "In addition, because obesity has been shown to be related to declining circulating testosterone levels, and reductions in sex hormone binding globulin (SHBG) associated with hyperinsulinemia in obese men, we also examined lipid and metabolic relationships with serum testosterone levels." (PMID 30865634, 2019). "Studies have suggested that obesity treatment increases SHBG levels from low levels in the obese and overweight state in patients with polycystic ovarian syndrome (PCOS)." (PMID 41404471, 2026). "Obesity only seems to contribute to the pathogenesis of PCOS, being associated with higher androgenic levels and lower SHBG." (PMID 39941345, 2025). "Obesity was linked to reduced sex hormone-binding globulin levels and higher HOMA-IR, while women with both PCOS and obesity had markedly elevated androstenedione and testosterone levels." (PMID 41011063, 2025). "A critical question remains: Is SHBG simply a biomarker of obesity and metabolic health, or does it act as an active contributor to metabolic regulation?" (PMID 41180177, 2025). "As a mediator between various endocrine tissues, SHBG plays a crucial pathophysiological role in obesity, osteoporosis, metabolic syndrome, and etc.." (PMID 39812542, 2025). "Sex Hormone-Binding Globulin (SHBG) levels are lowered in those with obesity, meaning more estrogen and testosterone are circulating." (PMID 40551741, 2025). "Obesity-related reductions in SHBG, testosterone's principal circulating carrier protein, are primarily responsible for measured reductions in testosterone." (PMID 40052430, 2025). "Sex hormone-binding globulin (SHBG) levels are also markedly reduced in obesity, limiting the bioavailability of androgens and oestrogens and amplifying endocrine imbalances." (PMID 41226484, 2025).